IFNG (interferon gamma)
Diseases named in the same sentence as IFNG in open-access papers (continued):
Sharing a sentence is not in itself a finding about the gene and the disease.
cancer (continued). "Meanwhile, the normal level of interferon gamma (IFNγ) related to the immune system is 5.0–45.0 pg/mL; it contributes to the anti-cancer activity of NK cells among immune cells." (PMID 39684992, 2024). "PD-L1 expression in cancer cells is upregulated by IFNγ and other pro-inflammatory cytokines released by activated lymphocytes and other immune cells in the TME." (PMID 39123403, 2024). "CAR-M cells secrete pro-inflammatory cytokines, such as interferon-gamma (IFN-γ), which recruit and activate other immune cells to further target cancer cells." (PMID 39659573, 2024). "In cancer, pro-inflammatory stimuli such as interferon gamma (IFN-γ) released by T cells have been shown to stimulate PD-L1 expression." (PMID 38638433, 2024). "The antitumor response efficacy of our TCR-Ts was evaluated against EADC and ESCC cells by quantifying the cytotoxicity and IFNγ release after an encounter with cancer cells or antigens." (PMID 38336680, 2024). "Disruption of IFNγ is also important in cancer progression by contributing to immune system paralysis." (PMID 38526562, 2024). "Research indicates that androgens can suppress T cell function and the production of IFNγ, directly affecting the effectiveness of T cell-targeted cancer immunotherapies." (PMID 38698844, 2024). "Much work is still needed to understand how to modulate IFNγ signaling to improve cancer therapy efficacy." (PMID 38684864, 2024). "Th1 CD4+ T cells directly kill cancer cells by producing interferon gamma (IFN-γ) and TNF-α, and they also assist cytotoxic CD8+ T cells and B cells in their antitumor activities." (PMID 38933335, 2024). "This review focuses on ICKs designed with the most impactful cytokines in the cancer field: IL-2, TNFα, IL-10, IL-12, IL-15, IL-21, IFNγ, GM-CSF, and IFNα." (PMID 39204319, 2024). "The analysis revealed a significant association between TAA-specific IFNγ+4-1BB+ CD8+ T cell response and pancreatic head and pancreatic body tail cancer (p = 0.0307)." (PMID 38550601, 2024). "In vitro analysis revealed that rNDV-2F2HN expressing human interferon-gamma had potential as a cancer therapeutic tool, particularly for immunized individuals." (PMID 38317245, 2024). "When cancer cells are exposed to IFNγ released by T cells, the SP subunits (β1c, β2c, β5c) are replaced by IP subunits (β1i, β2i, β5i)." (PMID 39116074, 2024). "In 1994, Schreiber and colleagues provided initial experimental evidence of immunosurveillance, by highlighting the crucial role of IFNγ signaling in cancer immunoediting." (PMID 38672681, 2024). "The responsiveness of cancer cells to interferon-γ (IFNγ) was estimated by evaluating IFNγ-mediated induction of target genes, STAT1 phosphorylation, HLA expression, and cell growth suppression." (PMID 39095793, 2024). "In contrast, the anti-angiostatic MIG, M-CSF, IL-10, and IFNγ cytokines in the host serum revealed a dramatic and significant decrease after day 5 post-implantation of cancer cells." (PMID 39451257, 2024). "These lipid peroxides accumulate in IFNγ-exposed cancer cells and trigger ferroptosis, a mode of cell death due to accumulation of oxidized lipids." (PMID 39284708, 2024). "For instance, activated human T cells are essential for the adaptive immune system, which helps fight cancer cells by infiltrating their microenvironment and secreting the cytokine interferon-γ (IFNγ)." (PMID 39154912, 2024). "Despite their low abundance, CD27+ IFNγ-producing γδ T cells provide significant protection from pathogens and cancer." (PMID 38816652, 2024). "In the study conducted by Zhao and colleagues on nasopharyngeal carcinoma, targeting HP1ß inhibited STAT1 activation via IFNγ, which led to lowered PD-L1 expression and, as such, enhanced cancer cell killing by CAR T-cells." (PMID 39519018, 2024). "PD-L1, upregulated by IFN gamma (IFNγ) and oncogenic signalling in cancer cells, plays a crucial role in inhibiting the killing activity of immune cells targeting cancer cells." (PMID 39375538, 2024).
cancer (continued). "On the other hand, glycosphingolipid metabolism, signaling by Wnt in cancer, interferon gamma signaling, biological oxidations, and sphingolipid metabolism were enriched in the NM group." (PMID 39507532, 2024). "CD8+ cytotoxic T cells, key players in antitumor immunity within the TME, release interferon-γ (IFNγ), which inhibits cystine uptake in cancer cells by downregulating SLC7A11 expression." (PMID 38322268, 2024). "Cancer cells are often exposed to IFNγ within the TME, and IFNγ is a well-known strong inducer of PD-L1 expression." (PMID 38729997, 2024). "We found QFM increased the anti-cancer actions of PD-1 inhibitors by increasing the CD8+IFNγ+ T cells infiltration and decreasing the ratio of Kyn/Trp." (PMID 38882349, 2024). "Since MHC-II expression in cancer cells depends on the interferon gamma (IFN-γ), we performed ELISA experiment to detect intracellular IFN-γ levels between KP and KPP cells." (PMID 38885192, 2024). "NF-κB signaling has the ability to induce PD-L1 expression in a multitude of different cancer subtypes, specifically through the production of IFNγ in T cells." (PMID 39623404, 2024). "It has been proposed that IFNG has an important role in immunoediting, which means reprogramming of cancer cells such that they survive immune-mediated cell death." (PMID 39123378, 2024). "When their receptors recognize the major histocompatibility complex on cancer cells, T cells become activated and secrete interferon γ (IFNγ)." (PMID 39744013, 2024). "STING protein was expressed at varying basal levels across cancer cell lines and was notably induced in response to IFNβ and/or IFNγ treatments." (PMID 38992037, 2024). "In summary, tumor-infiltrating activated CD8+ T cells and CAR-modified NK cells can kill cancer cells by enhancing their vulnerability to ferroptosis through the production and release of IFNγ." (PMID 38453898, 2024). "IFNγ neutralization abated M1-like TAMs and abrogation of cancer-cell responsiveness to IFNγ suppressed therapeutic response to DCP treatment." (PMID 37996514, 2024). "Cytotoxic T cells are activated through antigen presentation and induce cancer cell death by releasing cytotoxic proteins such as granzymes, perforin, and IFNγ." (PMID 39191486, 2024). "For instance, natural killer (NK) cells have the ability to identify and eliminate contaminated and aberrant cells, including cancer cells, through the initiation of apoptosis or the secretion of cytokines such as interferon-gamma (IFN-γ)." (PMID 39062056, 2024). "In response to IFNγ, cancer cells downregulate SLC7A11 and SLC3A2 expression, which together mediate cysteine import in mammalian cells." (PMID 39284708, 2024). "Mouse IFNγ-producing γδ-T cells are potent cancer-killing cells; however, their diversity and regulation by cytokines is poorly understood." (PMID 38816652, 2024). "IFNγ secretion was significantly decreased when cancer cells such as MCF-7 or HT-1080 cells and PBMCs were cocultured compared to that when T cell receptors (TCRs) were activated in human PBMC monocultures." (PMID 39105882, 2024). "Induction of soluble IFNγ and granzyme B by cancer cells were observed in culture supernatants and KO cells induced a marginal enhancement, as compared to the control cells." (PMID 38678024, 2024). "A similar but natural phenomenon occurs in human cancer cells, in which proteome-wide Trp-to-Phe substitutions arise from Trp depletion by IFNγ-mediated IDO1 induction." (PMID 39154912, 2024). "By activating STING, GAMP levels in the TME reduce the number of MDSCs and promote IFNγ secretion from cytotoxic antitumor effector cells, suppressing cancer metastasis." (PMID 38672681, 2024). "The results revealed the involvement of multiple genes in immune-related biological processes, including the defense response to protozoan, the response to interferon-gamma, MicroRNAs in cancer, the sphingolipid metabolic process, autophagy and endocytosis." (PMID 39273692, 2024).
cancer (continued). "The upregulation of IFNγ expression also leads to an increased expression of the antigen presentation machinery, enhancing cancer cell recognition and facilitating more effective killing." (PMID 38903504, 2024). "Of note, cytokines IL-12/15/18 stimulate murine and human NK cells to secret more IFNγ and hold great promise for cancer immunotherapy." (PMID 39081326, 2024). "IL-6 signaling pathway and IFNγ response were most significantly enriched in Bcl6 knockout cancer cells." (PMID 38956432, 2024). "The reduced IFNγ secretion observed in the coculture of PD-L1-expressing cancer cells and TCR-stimulated PBMCs was expected to be increased by pembrolizumab or atezolizumab treatment." (PMID 39105882, 2024). "IFNγ influence chemotherapeutic efficacy by regulating the immune effects of anti-cancer therapies as well as the ability of cancer cells to respond to genotoxic damage." (PMID 38684864, 2024). "Lymphocytes also release cytokines such as TNF and interferon-gamma to impede cancer cell development." (PMID 38935663, 2024). "To maximize assay versatility, we incorporated the IFNγ-IFNγR JAK-STAT GAS-Luc2 reporting system in the cancer cells so users can employ multiple kinds of primary human immune cells for the counterpart of the cancer cells in the full human co-culture assay." (PMID 38893085, 2024). "The cancer cells in immune-rich type tumors tended to have higher expression of interferon alpha and interferon gamma response genes." (PMID 36729271, 2023). "This trial serves as a proof of concept demonstrating that IFNγ can be utilised in the treatment of cancer." (PMID 37455828, 2023). "Using an ELISA assay, we confirmed that TNase depletion of tryptophan also limits the production of immunosuppressive kynurenine in IFNγ-stimulated MDA-MB-468 cancer cells." (PMID 37317329, 2023). "Triggers ROS storm, GSH depletion, GPX4 inactivation, and LOX catalysis, promote ferroptosis in cancer cells and enhance IFNγ and AA action." (PMID 38288118, 2023). "This interaction results in the expansion and activation of effector T cells, responsible for the direct or indirect killing of cancer cells, primarily through cytokine production such as Interferon gamma (IFN-γ) and tumor necrosis factor alpha (TNF-α)." (PMID 37516849, 2023). "Cytotoxic lymphocytes release IFNγ and are associated with improved survival in TNBC and other cancer types." (PMID 37169743, 2023). "In contrast, expression of GZMB (granzyme B, a serine protease stored in activated T and NK cells that induces cancer cell apoptosis) and IFNG (activates cytotoxic T cells) were significantly higher in tumors with MSI-H, TMB ≥ 10 mutations/mb and PD-L1 ≥ 1%." (PMID 37553332, 2023). "IFNγ can upregulate the expression of programmed-death ligand 1 (PD-L1) on the surface of cancer cells, which binds its ligand (PD-1) on the activated CD8+ T cells." (PMID 37190141, 2023). "LSECs and NK cells release interferon-gamma (IFNγ) and nitric oxide (NO) to upregulate Fas and induce apoptosis of cancer cells via the Fas–FasL pathway." (PMID 37480104, 2023). "Among the innate immune cells, interferon gamma (IFNγ)-activated NK cells are known to play a crucial role in eliminating cancer cells and cancer stem cells." (PMID 36902456, 2023). "Here the authors report that PARP14 is upregulated in chronic IFNγ-treated cancer cell models and that its inhibition restores response to anti-PD-1 therapy in preclinical cancer models." (PMID 37752135, 2023). "Interferon gamma coordinated the innate and adaptive immune response to viruses, bacteria and cancer." (PMID 36945884, 2023). "In the TIMER2.0 database, we further confirmed that in pan-cancer, IFNG had a general correlation with PD-L1 and CD8A." (PMID 36756126, 2023). "Within those, NK cells have a key role in anti-cancer immunity as they are an active component of the innate immune system and produce cytokines like interferon-gamma (IFN-γ) and tumor necrosis factor-alpha (TNF-α)." (PMID 38132355, 2023).
cancer (continued). "It is worth to note that Kupffer cells are liver macrophages resident with antitumor and antimetastatic activity through interferon gamma, interleukin-12, and other inflammatory mediators production that have cytotoxic effect on cancer cells." (PMID 37014499, 2023). "They suppress innate and adaptive immune systems, including suppressing of T-cells through prostaglandin E2, CXCL9, CXCL10, and CXCL11, and nitric oxide synthase in response to cancer cell-secreted TNFα, IFNγ, and IL-1." (PMID 37046676, 2023). "GC was found to promote TSC22D3 expression in dendritic cells, thereby blocking type-I IFN responses and IFNγ+ T-cell activation, which finally resulted in the compromise of therapy-induced anti-cancer immunosurveillance." (PMID 37210553, 2023). "Inhibiting SHP2 in cancer cells enhanced the signaling of IFNγ, leading to a rise in the expression of its downstream targets, such as chemoattractant cytokines and antigen-presenting machinery." (PMID 38001644, 2023). "As IFNγ has a direct antiproliferative effect on cancer cells, we used controls that included spheroids with IFNγ/Pam3SCK4 or IL-4 but without macrophages." (PMID 37445941, 2023). "Although intact IFNγ signaling in cancer cells is critical for checkpoint inhibitor efficacy, it is still unclear which specific IFNγ-induced molecular changes are responsible for this dependency." (PMID 37991387, 2023). "Co-culturing the NK cell line with several cancer cell lines, along with the addition of mAb14, enhanced the NK cell anti-cancer activity in terms of interferon gamma (IFN-γ) secretion and cancer cell cytotoxicity." (PMID 37686697, 2023). "These evidences collectively suggest the possible clinical benefits of IFNγ in cancer treatment that have been increasingly acknowledged." (PMID 37671945, 2023). "IFNγ alters the immunopeptidome presented on HLA class I (HLA-I), and its activity on cancer cells is known to be important for effective immunotherapy responses." (PMID 37991387, 2023). "Higher serum-induced IFN/ISG response levels thus seem to be associated with suppression of distant metastases, possibly via the involvement of IFNγ in cancer immune surveillance." (PMID 37759086, 2023). "CD107a, granzyme B and IFNγ have been reported as effector function markers for the cytolytic activity of γδ T cells and other cytotoxic immune cells when encountering cancer cells." (PMID 37835538, 2023). "As we found after stimulation of cancer cells with IFNγ/Pam3SCK4, cancer cells begin to secrete CXCL10." (PMID 37445941, 2023). "Our previous study demonstrated that blocking IFNγ was an efficient way to prevent doxorubicin-induced cardiotoxicity 36, which supports the application of anti-IFNγ antibody for the benefits of cancer patients." (PMID 37056922, 2023). "There, it enables NK cell survival by upregulating antiapoptotic gene expression, migration activity, and interferon-gamma production, leading to NK cell killing of cancer cells and antimetastatic effects in mice." (PMID 37046676, 2023). "The T lymphocytes and NK cells recognize the cancer cells and produce interferon gamma (IFNγ) and cytokines." (PMID 36946842, 2023). "Fourth, NK cells can also secrete IFNγ to induce cancer cell death and regulate other cancer-fighting immune cells." (PMID 38022646, 2023). "Peptides with proline in positions 4 and 5, which favors peptide downregulation or even makes them undetectable in cancer cells exposed to IFNγ, can be avoided." (PMID 37991387, 2023). "TNF-α, in combination with interferon gamma (IFN-γ), has also been used to induce senescence in cancer cells." (PMID 38132089, 2023). "IFNγ, a secreted cytokine, was included in this panel based on data from a murine PD-1 blockade model demonstrating that it is capable of killing target cancer cells via ferroptosis." (PMID 37055388, 2023).
cancer (continued). "Particularly, factors related to epithelial-mesenchymal transition, TNFA, and IL6/JAK/STAT signaling were elevated in basal cancer cells along with signatures for inflammatory response and IFNG response." (PMID 37633924, 2023). "IDO1 and TDO can be expressed constitutively by cancer cells, in which case they inhibit lymphocyte infiltration, or expressed by cancer and stromal cells in response to IFNγ, which limits the activity of tumour-infiltrating lymphocytes." (PMID 37936700, 2023). "categorized CeCa into two (of 6 established) pan-cancer immune phenotypes - C1 (“wound-healing”) and C2 (“IFNγ-dominant”)." (PMID 37731500, 2023). "Myricetin also reversed the loss of Jurkat cell proliferation and IL-2 production induced by IFNγ-treated cancer cells." (PMID 37296860, 2023). "IFNγ is a pleiotropic cytokine that can boost anti-tumorigenic activities through various mechanisms, but at the same time, can promote cancer cell growth." (PMID 36839699, 2023). "CIITA plays a particularly important role in the process of IFNγ-initiated MHC-II expression, while some cancer cells appear insensitive to IFNγ stimulation." (PMID 37508545, 2023). "Initially discovered as an anti-viral cytokine, IFNγ also plays a critical role in the interaction between cancer and the immune system." (PMID 38130991, 2023). "To explore the possible roles of IFNG in carcinogenesis, we first analyzed its expression in the TCGA pan-cancer." (PMID 36756126, 2023). "These pathways encompass Glycolysis, TGF Beta signaling, PI3K/AKT/MTOR signaling, as well as Interferon Alpha and Interferon Gamma Responses across various cancer types." (PMID 37762224, 2023). "A screen of several varieties of cancer cells revealed compounds that prevented IFNγ induction of the IDO and PD-L1 checkpoint molecules." (PMID 37296860, 2023). "PD-L1-upregulated expression on cancer cells occurs via four primary mechanisms: (I) the DNA damage signaling pathway; (II) interferon gamma (IFN-γ) signaling; (III) the cGAS-STING pathway; and (IV) the epidermal growth factor receptor (EGFR) pathway." (PMID 37887283, 2023). "We discovered that TNFA signaling through NFKB, KRAS signaling, epithelial-mesenchymal transition (EMT), the inflammatory response, hypoxia, and the interferon-gamma response, were all remarkably correlated with OMRGs in pan-cancer." (PMID 36860371, 2023). "A recent study also found more than half of the tested cancer cell lines to be resistant to IFNγ-mediated growth inhibition." (PMID 37803324, 2023). "Whilst type I and type III IFNs predominantly protect the host from pathogens, IFNγ being the sole member of type II IFNs, has additional well-documented functions in cancer immunosurveillance." (PMID 37455828, 2023). "Conversely, it has been demonstrated in other cancer types that conditioned media from M1 (LPS + IFNγ -treated) macrophages can inhibit cancer cell proliferation." (PMID 40838054, 2023). "AC484 treatment potently sensitized cancer cells to IFNγ and enhanced the activation and effector functions of T cells and NK cells." (PMID 37794185, 2023). "We treated a panel human cancer cell lines of diverse origins and two patient-derived liver tumor organoids with IFNγ alone or IFNγ plus FSK." (PMID 37714844, 2023). "IFNγ induces cancer cell senescence and arrest via activating p16Ink4a/p19Arf and p21Cip1 thereby inhibiting tumorigenesis in models of pancreatic islet cancer and Burkitt lymphoma." (PMID 37455828, 2023). "The activated CD8+ T cells secrete high amounts of IFNγ which then feeds back on the cancer cells to further upregulate CRC cell MHCI, further increasing their capacity to activate CD8+ T cells." (PMID 37304266, 2023). "Pathway analysis showed that PANoptosis score was positively correlated with pathways linked to immune and inflammatory responses in pan-cancer, such as IL6-JAK-STAT3 signaling, the interferon-gamma response, and IL2-STAT5 signaling." (PMID 36890219, 2023).